LOXL2 (lysyl oxidase like 2)
Diseases named in the same sentence as LOXL2 in open-access papers (continued):
Sharing a sentence is not in itself a finding about the gene and the disease.
tumor (continued). "Based on the results of the multivariate analysis, older age (≥65 years), gender (male), tumor location (head), portal vein invasion, perineural invasion, UICC stage, mesenchymal EMT status and high LOXL2 expression were independent predictive factors for OS in patients with PC." (PMID 29959362, 2018). "While the stromal labelling differed to some extent between tumours and in different regions of the same tumour, we saw no consistent effects of Loxl2 expression." (PMID 29953488, 2018). "Lysyl Oxidase Like 2 (LOXL2), one of the lysyl oxidase (LOX) family members and a matrix remodeling enzyme, promotes ECM remodeling, triggers EMT program and contributes to tumor progression and metastases." (PMID 30456206, 2018). "However, we hypothesize that the effects of LOXL-2 inhibition, either genetically or pharmacologically, and enzymatic or non-enzymatic, are not direct, but as a result of other changes to tumor physiology given the observed significant reduction in primary tumor volume in both models." (PMID 28199967, 2017). "Overall, our results demonstrate that expression of LOXL2 endowed DTC with CSC-like phenotype driving their transition to metastatic outgrowth and this stem-like phenotype is dependent on EMT that can be driven by the tumor microenvironment." (PMID 27655685, 2016). "Tumor samples from the breasts of mice in model group, escin Ia (2 mg/kg, 4 mg/kg)-treated groups and BAPN (100 mg/kg)-treated groups were used to determine the effect of escin Ia on the expressions of HIF-1α, LOXL2 and EMT markers." (PMID 27008697, 2016). "The invasion of tumor cells could be regulated by many factors such as BRMS1, E-cadherin, Keratin19, LOXL2, MMP9, Orai1, Stim1, TGF-β and VEGF." (PMID 27008697, 2016). "Intriguingly, only the subpopulation of cells with CSC-like properties mediated the outgrowth of the dormant tumor cells, whereas the rest of the cells expressing LOXL2, which do not display CSC-like properties, remained dormant in the 3D BME system." (PMID 27655685, 2016). "Intracellular LOXL2 is able to positively regulate the epithelial-mesenchymal transition (EMT) inducer Snail by enhancing Snail stability and functional activity and promoting EMT and tumor progression through downregulation of E-cadherin." (PMID 25254241, 2014). "Several tumor-related genes such as ERO1L, ITGA3, and MAPK8 were found closest to LOXL2-e13." (PMID 25254241, 2014). "LOXL2 has been found to act in the nucleus of cancer cells and deaminates the lysine 4 amino group of H3 leading to downregulation of CDH1, decreased E-cadherin expression, fewer cellular adhesions facilitating tumour growth and metastases." (PMID 23125850, 2012). "Crosslinking of collagen by LOXL2 may stimulate matrix metalloproteinases such as MMP9 and TIMP1 to implement ECM remodeling (interaction 20), thereby facilitating tumor cell migration." (PMID 22570691, 2012). "In contrast, experimental manipulation of ECM with an anti‐LOXL2 antibody in syngeneic orthotopic pancreatic ductal adenocarcinoma (PDA) mouse models resulted in a significant decrease in ECM content, decreased tissue stiffness, and accelerated tumor growth, resulting in decreased overall survival." (PMID 39801760, 2025). "Therefore, in KL tumors, whether LOXL-2 is a key regulator contributing to activated FAK pathway in CAF needs to be further investigated; and (iii) TME features in subcutaneous tumor models might be distinct from that in orthotopic tumors." (PMID 38291516, 2024). "However, the roles of the LOXL2 gene in mechanisms of oncogenesis and tumor development have not been clearly defined." (PMID 38922489, 2024). "Unlike LOX, LOXL2 crosslinks and stabilizes insoluble collagen deposition in tumor tissues." (PMID 39329988, 2024).
tumor (continued). "Notably, the apoptotic capacity of tumor cells was significantly enhanced by silencing LOXL2 but not significantly decreased by overexpression of LOXL2, but this was considered to be related to the KYSE cell background apoptotic capacity threshold." (PMID 36995521, 2023). "Moreover, several studies have indicated that LOXL2 may act as an adaptive response protein to promote VEGFA secretion and tumor angiogenesis." (PMID 37056396, 2023). "The role of LOXL2 and BRD4 in DNA damage and their cooperation in controlling the transcriptional regulation of cell cycle progression may suggest that their simultaneous inhibition in tumor cells could act as a double‐edged sword." (PMID 37937685, 2023). "In patients with locally advanced disease, positive LOXL2 expression was highly correlated with tumor T stage and lymph node metastasis, suggesting that LOXL2 may promote the progression of ESCC through its involvement in tumor proliferation and metastasis." (PMID 36995521, 2023). "Therefore, we investigated whether LCN2, LOXL2, and MMP9 are interrelated in ECM remodelling, and whether LCN2/LOXL2/MMP9 form a complex to play a synergistic role in tumour progression." (PMID 37753805, 2023). "Detailed analysis of the clinicopathological parameters and cellular and molecular characterisation of the four models and derived cell lines established that Loxl2 depletion significantly decreased metastasis and increased overall survival without affecting primary tumour development and growth." (PMID 37762708, 2023). "Indeed, pre-treatment of orthotopic PDAC (KPC + PSC co-inoculated) mice with a lysyl oxidase-like 2 (LOXL2) inhibitor disrupted collagen alignment without altering content, softened tumor tissue, and improved the therapeutic efficacy of nab-paclitaxel." (PMID 36765684, 2023). "Furthermore, the silencing of miR-92a could significantly suppress tumor invasion and growth, while the enhancement of miR-29a expression levels could also put a break on metastatic dissemination via targeting VEGFA, LOXL2, and LOX." (PMID 37108330, 2023). "Moreover, elevated expression of LOXL2 as a result of hypoxic stress has been found to modulate gene transcription and to promote epithelial-to-mesenchymal transition (EMT), contributing to the enhancement of tumor cell motility, invasiveness and metastasis." (PMID 36209516, 2022). "However, the contribution of the non-enzymatic functions of LOXL2 to tumor progression has not yet been studied in depth." (PMID 36209516, 2022). "Therefore, the complex tumor-stromal interaction of LOXL2 in PDAC tumorigenesis requires further investigation and re-evaluation of the efficacy of using anti-LOXL2 antibodies or small molecule LOXL2 inhibitors in the treatment landscape of metastatic PDAC." (PMID 36010993, 2022). "LOXL2, secreted in vesicles in response to hypoxia, not only acts in the premetastatic niche but can also reach cells of the primary tumor that are not under hypoxic conditions, which helps them carry out epithelial–mesenchymal transition and initiate invasion from nearby tissues." (PMID 36497411, 2022). "One limitation of this study is the fact that monoclonal antibodies chiefly inhibit the extracellular LOXL2, but do not affect the activity of intracellular LOXL2, which might play a role in tumor progression as well." (PMID 34948209, 2021). "Therefore, comparing OSM mRNA expression from tumor samples directly against LOXL2 would not yield a highly relevant correlation." (PMID 34011405, 2021). "We also do not take into account other mechanisms whereby LOXL2 (or other Lysyl Oxidases) can enhance tumor aggressiveness; these certainly include angiogenesis, pre-metastasis niche formation, drug resistance and the growth of lymphatic vessels at least partially due to upregulation of VEGF." (PMID 33807227, 2021).
tumor (continued). "By contrast, in vivo modulation of tumor cell morphology, E-cadherin and vimentin levels, and the lack of in vitro inhibition of tumor cell proliferation by the LOXL2 inhibitor, point to a possible EMT function rather than proliferative stimulation of tumor cell growth." (PMID 31086173, 2019). "Moreover, this study provides the first molecular mechanism for enzymatically active LOXL2 in the promotion of cancer via its modification of a non-collagenous substrate in the context of paracrine signaling between tumor cells and resident fibroblasts." (PMID 31086173, 2019). "LOXL2 is a member of the lysyl oxidase gene family which catalyzes the crosslinking of extracellular collagen and elastin resulting in increased ECM stiffness and subsequent activation of the kinases FAK and SRC, which enable tumor cells to proliferate and invade." (PMID 30473751, 2018). "In addition, TGFβ-induced lysyl oxidase-like 2 (LOXL2) transcription may also contribute to HCC intrahepatic and extrahepatic metastasis by modifying the tumour microenvironment and metastatic niche." (PMID 27586372, 2017). "To further confirm that it was the specific inhibition of tumor-secreted LOXL2 responsible for driving tumor angiogenesis, and not stromal inhibition as a result of systemic treatment with the inhibitors, we also evaluated endomucin scoring in our two stable shLOX2 models." (PMID 28199967, 2017). "In addition, LOXL2 catalyses the deacetylation of fructose-bisphosphate aldolase A (ALDOA) at K13, leading to the mobilisation of aldolase A from the cytoskeletal to the cytosolic fraction, which enhances glycolysis and subsequently promotes tumour progression." (PMID 37762708, 2023). "The other risk factors LOXL1, LOXL2, and STEAP3 were highly expressed in almost all tumor zones (CT, HBVs, MVP, PAN, PNZ, IT) and showed the lowest expression in the peritumor zone (LE), while the protective factor F5 showed no obvious change between the tumor and peritumor zone." (PMID 37891828, 2023). "Some studies also show that pro-metastatic function of LOXL-2 is independent of its role in ECM remodeling; others show that increased LOX secretion in the same tumor type increases matrix stiffening through collagen crosslinking, causing tumor cell dissemination and metastasis." (PMID 33639646, 2021). "Furthermore, Loxl2 expression did not alter the stroma of DMBA-TPA-induced tumours." (PMID 29953488, 2018). "In HCC cells, several studies showed that the miR-29-3p-family acted as tumor-suppressive miRNAs via negative control of several oncogenic targets, e.g., IGF2BP1, RPS15A and LOXL2." (PMID 34199886, 2021). "In the present study, we demonstrated that hypoxic HNSCC cell-derived sEVs induce cell invasion from the primary tumor and adhesion of non-hypoxic HNSCC cells on the second lesion site by delivering LOXL2." (PMID 34646366, 2021). "Addition of TGF-β to tumor cell-N-MSC co-culture augmented MX2, BST2 and IL6 (right columns) but not ADAMTS12, LOXL2 GREM1 or CHI3L1 expression in N-MSCs." (PMID 29503225, 2018). "Meanwhile, elevated LOXL2 expression can promote VE-cadherin expression, facilitating the formation of VM channels in HCC cells, providing a non-endothelial-dependent blood supply for the tumor." (PMID 41019994, 2025). "In the nucleus, LOXL2 binds specifically to the short isoform of BRD4 (BRD4S) that in TNBC has been recently describe as oncogenic, but not to the long one (BRD4L), which has a tumor suppressive role." (PMID 37937685, 2023). "Conclusion: sEVs derived from the hypoxic tumor microenvironment of HNSCC can drive local invasion of non-hypoxic HNSCC cells and stimulate premetastatic niche formation by delivering LOXL2 to non-hypoxic HNSCC cells and fibroblasts to induce EMT and fibronectin production, respectively." (PMID 34646366, 2021).
tumor (continued). "More accurately, tumor stroma might play an important role in negative immunoregulation since the hub genes (i.e., CTHRC1, COL1A1, LOXL2, P4HA3, and FKBP10) related to immunosuppressive GO terms usually participate in collagen formation." (PMID 33791227, 2021). "However, in our samples, the four genes were expressed in T-MSCs, and more modestly in N-MSCs but not (GREM1 and LOXL2) or weakly so (ITGA11 and ADAMTS12) in the tumor cells (data not shown)." (PMID 29503225, 2018). "Furthermore, Western blotting assay indicated that the expression of NID1 was consistent with ETV4 and LOXL2 in paired non-tumor and tumor tissues samples (n=4), and the correlation analysis on human CRC cDNA array showed that NID1 was positively correlated with ETV4 and LOXL2, respectively." (PMID 41281746, 2025). "Studies of mechanisms in vitro support that tumor cell-derived LOXL2 directly stimulated stromal fibroblast proliferation and activity by enhancing PDGF-AB-mediated signaling after modification of PDGFRβ, while having no proliferative effect on tumor cells themselves." (PMID 31086173, 2019).
cancer (204 papers, 2004 to 2026). A tumor composed of atypical neoplastic, often pleomorphic cells that invade other tissues. "Elevated levels of CTSD and LOXL2 were found in various tumors and patient plasma samples, and CTSD as well as LOXL2 have been consistently associated with unfavorable prognosis across various cancers." (PMID 41185039, 2025). "Loss of miR-29 expression has been linked to increased cancer cell invasion and migration, primarily through the upregulation of oncogenic targets like lysyl oxidase-like 2 (LOXL2)." (PMID 40332376, 2025). "Our initial comprehensive analysis of LOXL2 across diverse cancer types revealed its prevalent overexpression and association with unfavorable clinical results, subsequent genetic alterations, and immunological context." (PMID 38922489, 2024). "Our initial comprehensive examination of LOXL2 across various cancer types revealed its prevalent overexpression and association with unfavorable clinical results." (PMID 38922489, 2024). "LOXL2 has been identified as a carcinoma promotor since 2003, for its underlying roles in maturation and remodeling of ECM as an extracellular enzyme." (PMID 38922489, 2024). "The EMT activator ZEB1, which is implicated in regulating dormancy and reawakening of cancer cells, can upregulate LOXL2 through direct binding to its promoter." (PMID 37442876, 2023). "LOXL2 has also been implicated in the development of various fibrotic diseases and cancer due to its ability in intracellular signaling of epithelial-mesenchymal transition as well as ECM remodeling." (PMID 37029269, 2023). "Apart from GEMMs, numerous gain and loss of function studies of LOXL2 in different human cancer cell lines tested in xenografted models in immune compromised mice have been reported in the last two decades." (PMID 37762708, 2023). "Regarding to LOXL2 point mutations, our screening revealed mutations in 1.37% of cancer samples (151 out 10,953), with 15 samples showing multiple LOXL2 mutations." (PMID 37762708, 2023). "A variety of studies have reported that dysregulation of LOXL2 is strongly associated with cancer progression and fibrosis-related diseases." (PMID 35246120, 2022). "LOXL2 is overexpressed in some cancers, thus contributing to poor prognosis and a higher risk of distant metastases." (PMID 33669630, 2021). "LOXL2, a prototypical lysyl oxidase, is implicated in the promotion of cancer cell invasion, metastasis and angiogenesis, as well as in the malignant transformation of solid tumors." (PMID 34943209, 2021). "Several splice variants of LOXL2 have been reported in various cancers, including esophageal squamous cell carcinoma." (PMID 33804181, 2021). "Upregulation of LOXL2 has been observed in a number of human cancers, and its expression has been associated with cancer aggressiveness." (PMID 33544155, 2021). "For predicting potency, the high-LOXL2 cluster showed younger mean diagnostic age, with poorer cancer outcome in the 20–39 age range." (PMID 32211324, 2020). "LOXL2 has been implicated in promoting cancer cell proliferation, invasion, metastasis, and angiogenesis in many cancer types." (PMID 32211324, 2020). "Deregulated expression of LOXL2 has been implicated in the development of fibrosis and cancer in a variety of tissues and organs." (PMID 29953488, 2018). "Although increased LOXL2 expression is reported to be associated with malignant aggressiveness in various cancer cells, a very limited number of studies have examined LOXL2 expression in PC23." (PMID 29959362, 2018). "LOXL2, in particular was implicated to play a key role in the development of fibrosis in liver and lung as well as in cancer progression where a fibrotic microenvironment facilitates motility and invasion." (PMID 29930330, 2018). "In vitro stimulation of cancer-associated fibroblasts with recombinant LOXL2 significantly increased the expression of fibronectin mRNA8." (PMID 29930330, 2018).